RN7SL811P (RNA, 7SL, cytoplasmic 811, pseudogene)
Gene: Miscellaneous RNA gene on chromosome 6 (44,209,766 to 44,210,063, forward strand). Ensembl gene ENSG00000265439.
Homologues: Paralogues in human: RN7SL134P (84% identical), Metazoa_SRP (82% identical), RN7SL784P (82% identical), RN7SL96P (82% identical), RN7SL474P (82% identical), RN7SL774P (81% identical), Metazoa_SRP (80% identical), RN7SL163P (80% identical), RN7SL596P (79% identical), RN7SL123P (79% identical), RN7SL154P (79% identical), Metazoa_SRP (79% identical), and 711 more.